VAV1 (vav guanine nucleotide exchange factor 1)
Diseases named in the same sentence as VAV1 in open-access papers (continued):
Sharing a sentence is not in itself a finding about the gene and the disease.
lung carcinoma (15 papers, 2012 to 2024). "For instance, high-intensity VAV1 expression was associated with larger lung cancer tumor size, MBSHH tumors, gastric cancer, and ESCC." (PMID 37174676, 2023). "Several of the mutations identified in lung cancer as well as hematological malignancies lead to increased VAV1 GEF activity, such as Y174C, E175K, E175V/L, L177R, K404R, Q498K/R, M501R/L/N, E556D/K, and P615L." (PMID 37174676, 2023). "Like OPN in HCC, over-expression of Vav1 protein in PDAs and lung cancers is associated with poor prognosis." (PMID 22253833, 2012). "However, when crossed with mice expressing mutant KRAS in the lung, NSCLC tumors developed, clearly demonstrating that oncogenic mutants of VAV1 act synergistically with mutant KRAS to cause lung cancer." (PMID 37174676, 2023). "VAV1 is tyrosine phosphorylated in lung cancer cells upon activation by growth factors EGF and TGFα, suggesting its involvement in signaling pathways in non-hematopoietic tissues." (PMID 37174676, 2023). "Mutations in putative transcription factor binding sites in the VAV1 promoter were shown to modify VAV1 transcription in lung cancer cell lines." (PMID 37174676, 2023). "VAV1 expression was also detected in 42% (33/78) of lung cancer cell lines and 44% (26/59) of primary human lung cancer tissue samples." (PMID 37174676, 2023). "VAV1-dependent growth factor secretion was shown to occur in lung cancer cells that ectopically express the gene." (PMID 37174676, 2023). "Similar results were obtained in human lung cancer cell lines, where the siRNA-mediated knockdown of VAV1 suppressed growth on agar and suppressed tumor growth in nude mice." (PMID 37174676, 2023). "Another core gene, Vav1, accelerates Ras-driven lung cancer and regulates its tumor microenvironment and its mutations can cause different human oncogenic phenotypes." (PMID 36744181, 2022). "The importance of this activity for Vav1 function was previously demonstrated in pancreatic and lung cancers, where it is ectopically overexpressed." (PMID 30297765, 2018). "The association between Vav1 expression and CSF1 was further supported by signal transduction experiments, pointing to the involvement of Vav1 in regulating the lung cancer secretome." (PMID 26353933, 2015). "It is noteworthy that lung cancer cells depleted of Vav1 also showed a decrease in EGF and TGFα, further highlighting the association between Vav1 expression in cancer cells and the expression of autocrine/paracrine growth factors." (PMID 26353933, 2015). "H358 and H441, two human lung carcinoma epithelial cell lines exhibit substantial amounts of Vav1 proteins compared to a lymphoid cell line (Raji)." (PMID 25426554, 2015). "Among these sites is a consensus site for c-Myb, a hematopoietic-specific transcription factor also found in Vav1-expressing lung cancer cell lines." (PMID 26353933, 2015). "We demonstrated Vav1 expression in malignant human lung cancer specimens (~44%) and in human lung cancer cell lines (~42%)." (PMID 25313137, 2014). "Our current studies demonstrate for the first time, that Vav1 is tyrosine phosphorylated in response to CSF1 in lung cancer cells, thus suggesting a supportive role for Vav1 as a universal signal transducer in cancer." (PMID 25313137, 2014). "One of the most intriguing results from our current studies is that lung cancer cells depleted of Vav1 exhibit significantly reduced levels of CSF1, suggesting that Vav1 propagates an autocrine feed forward loop by upregulating expression of growth factors." (PMID 25313137, 2014). "The association between Vav1 expression and CSF1 was further supported by signal transduction experiments, supporting involvement of Vav1 in regulating lung cancer secretome." (PMID 25313137, 2014). "Knocking down of vav1 gene in lung cancer and pancreatic cells leads to the decreased cell proliferation and reduces tumor size in nude mice." (PMID 24905577, 2014).
lung carcinoma (continued). "Similar to our results with CSF1, in lung cancer cell lines, TGFα leads to an increase in tyrosine phosphorylation of Vav1, while depletion of Vav1 reduces TGFα expression." (PMID 25313137, 2014). "We demonstrate that lung cancer cells that abnormally express Vav1 secrete growth factors in a Vav1-dependent manner." (PMID 25313137, 2014). "Aberrant expression of Vav1 was also found in over 40% of human primary lung cancers and lung cancer cell lines examined and in melanoma tissue sections and cell lines." (PMID 23342133, 2013). "Depletion of Vav1 expression in pancreatic and lung cancer cell lines reduced colony formation in soft agar and tumor size in nude mice." (PMID 23342133, 2013). "Depletion of Vav1 in lung cancer cells decreased expression of TGFα, an autocrine growth factor that activates these cells." (PMID 23342133, 2013). "Among these sites is a consensus site for c-Myb, a hematopoietic-specific transcription factor that is also found in Vav1-expressing lung cancer cell lines." (PMID 22253833, 2012). "Aberrant expression of Rac exchange factors (Rac-GEFs) Ect2 and Vav1/2/3 has been reported in lung cancer, suggestive of a crucial role for the Rac signaling pathway in the progression of the disease." (PMID 22384062, 2012). "Consistent with this, co-transfection of c-Myb activated transcription of a vav1 promoter-luciferase reporter gene construct in lung cancer cells devoid of Vav1 expression." (PMID 22253833, 2012). "It is reasonable to suggest that other members of the ETS family bind to the consensus sequence in the vav1 promoter in lymphoid Jurkat T cells and H441 lung cancer cells." (PMID 22253833, 2012). "Down-regulation of c-myb by transfection of siRNA into H441 lung cancer cells significantly decreased vav1 expression." (PMID 22253833, 2012). "Recently, Vav1 was shown to be involved in several human malignancies including neuroblastoma, lung cancer, and pancreatic ductal adenocarcinoma (PDA)." (PMID 22253833, 2012). "Our current study reveals the involvement of the hematopoietic transcription factor c-Myb in the expression of vav1 in lung cancer cells." (PMID 22253833, 2012). "Also, diminished Vav1′s expression in lung cancer cell lines reduced the expression of the growth factors, TGFα and EGF, and CSF-1, which led to reduced tumorigenicity." (PMID 35326399, 2022). "Furthermore, Vav1 RNA interference was found to diminish proliferation of human pancreatic and lung cancer cell lines in vitro and in vivo, even in the presence of oncogenic K-Ras12,14." (PMID 30297765, 2018). "In this study, we investigated whether several amino acid substitutions in Vav1 at residues identified in human lung cancer patients acquire transforming properties, an attribute that can could credibly explain their potential involvement in human cancer." (PMID 30297765, 2018). "Indeed, we recently demonstrated that ERK phosphorylation is dependent on Vav1 activation in lung cancer cells." (PMID 26353933, 2015). "In addition, aberrant expression of Vav1 was found in 42% of 78 lung cancer cell lines examined, in 46% of 57 human primary lung cancer specimens and in breast, ovarian and prostate cancers." (PMID 26353933, 2015). "Interestingly, Vav1 expression was required for proliferation even in the presence of mutant K-Ras in pancreatic and lung cancer, demonstrating the critical role of Vav1 in tumor development." (PMID 26353933, 2015). "Recently, Vav1 was shown to be involved in diverse human cancers, including lung cancer." (PMID 25313137, 2014). "Meanwhile, evidence unveils the non-hematopoietic expression profile of Vav1, which associates with several human tumor malignancies, such as neuroblastoma, lung cancer, and pancreatic ductal adenocarcinomas." (PMID 24905577, 2014). "Indeed, Vav1-depletion in pancreatic and lung cancer cell lines results in the reduction of colony formation in soft agar in vitro and reduction of tumor size in immunocompromised mice." (PMID 25313137, 2014).
lung carcinoma (continued). "Indeed, depletion of Vav1 in lung cancer cells led to reduced ERK phosphorylation despite stimulation with CSF1." (PMID 25313137, 2014). "Then, we stimulated H358 lung cancer cells, known to express high levels of Vav1, with CSF1." (PMID 25313137, 2014). "siRNA-mediated knockdown of Vav1 in human lung cancer cells reduced proliferation in agar and tumor growth in nude mice, despite the presence of mutant K-Ras in these cells, suggesting that Vav1 plays a critical role in lung cancer." (PMID 25313137, 2014). "Our preliminary results pointed to the possibility that lung cancer cells that ectopically express Vav1 (H358) also secrete CSF1, a hematopoietic growth factor that stimulates monocyte proliferation and differentiation into macrophages and can activate Vav1 in immune cells." (PMID 25313137, 2014). "One transcription factor that might affect the level of vav1 expression in lung cancer cells is c-Myb." (PMID 22253833, 2012). "Together, these results indicate that c-Myb is involved in vav1 expression in lung cancer cells." (PMID 22253833, 2012). "We found that lung cancer cells depleted of Vav1 exhibit significantly reduced levels of the hematopoietic growth factor CSF1, suggesting that Vav1 propagates an autocrine feed forward loop by upregulating expression of growth factors." (PMID 26353933, 2015). "Remarkably, we found a significant positive correlation between expression of Vav1 and CSF1 in these primary human lung cancer specimens (p<0.05)." (PMID 25313137, 2014). "This intricate signaling pathways in which Vav1 and CSF1 are involved results on one hand in control of CSF1 expression in lung cancer cells and on the other hand, Vav1 stimulation by CSF1, thus evoking cytoskeleton organization and increased tumorigenicity." (PMID 25313137, 2014). "A number of groups, including ours, have detected the ectopic expression of Vav1 in neuroblastoma, pancreatic ductal adenocarcinomas (PDA) and lung cancer." (PMID 22253833, 2012). "Furthermore, VAV1 and CSF1 expression were positively correlated with tumor grade by immunohistochemical analysis of primary human lung cancers." (PMID 37174676, 2023). "Vav1 instigated TME by fibrosis enhancement and reduction in tumor infiltrating macrophage, which was due to cross-talking with colony-stimulating factor 1 (CSF1) pathway, favoring lung cancer growth." (PMID 37033636, 2023). "As these results suggest that CSF1 may be a major mediator of a Vav1 dependent loop, we next wished to determine whether CSF1 leads to Vav1 tyrosine phosphorylation in lung cancer cells." (PMID 25313137, 2014). "Our previous experiments indicated that lung cancer cells, H358, which ectopically express Vav1 can be grown in medium lacking growth factors for several days, thus suggesting that these cells secrete growth factors that support their growth." (PMID 25313137, 2014). "Indeed, Vav1 was shown to be tyrosine phosphorylated following EGF stimulation of neuroblastoma, pancreatic and lung cancer cells." (PMID 25313137, 2014). "Thus, it has been suggested that lung cancer may involve interactions between cancer cells and the microenvironment regulated via the CSF1/VAV1 signaling pathway." (PMID 37174676, 2023). "Finally, the correlation we observed between combined Vav1 positive/CSF1 positive expression and tumor grade further strengthens our conclusion that these proteins act together in a feed-forward loop that contributes to tumorigenicity in human lung cancer." (PMID 25313137, 2014). "Following transfection, luciferase was expressed at high levels in the Vav1-expressing cells (Jurkat, U937 and H441), but its expression level was very low in the vav1-negative cell lines (H460, A549 and Panc1) Luciferase expression in H441 lung cancer cells was even higher than in Jurkat T cells." (PMID 22253833, 2012).
lung carcinoma (continued). "Thus, combined Vav1 and CSF1 expression correlates with tumor grade in human lung cancer samples, providing support for the hypothesis that Vav1 and CSF1 might have converging roles in lung cancer development." (PMID 25313137, 2014).
leukemia (14 papers, 2009 to 2025). A malignant (clonal) hematologic disorder, involving hematopoietic stem cells and characterized by the presence of primitive or atypical myeloid or lymphoid cells in the bone marrow and the blood. "To evaluate the potential role of PHF6 mutation in leukemia-initiating events, we generated Phf6 knockout (Vav1-Cre;Phf6fl/y) and wild-type (Phf6fl/y) mice." (PMID 34465864, 2022). "Upon expression under the control of the Vav1 promoter, hSTAT5BN642H triggered leukemia or lymphoma development, which manifested as a transplantable CD8+ T cell disease." (PMID 38802512, 2024). "A recent study showed that VAV1 acts as a tumor suppressor in leukemia by promoting the degradation of ICN1 (intracellular domain of Notch1), while VAV1 mutation facilitates the malignant transformation of T cells." (PMID 34335756, 2021). "Vav1 inhibition using dasatinib, which is already used against leukemia, reduces TCR-stimulation in lymphoma cells." (PMID 34359851, 2021). "The expression of the VAV1 gene was followed in the 697 cancer human Pre-B leukemia cell line because in MJ90 hTERT fibroblasts the gene is expressed at very low levels." (PMID 32570830, 2020). "All leukemias detected in Vav1−/− mice consistently lack membrane expression of the TCR and are arrested at either the DN or ISP developmental stages." (PMID 29136506, 2017). "It will be really important in the future to obtain a large group of T–cell lymphoma/leukemia samples in order to assess the specific implication of Vav1 and RasGRF2 in this tumorigenic context." (PMID 20011522, 2009). "A number of these regulators have been shown to be identical in immune cells and cardiomyocytes (e.g., LARG (leukemia-associated RhoGEF), GEF-H1/Lfc (Lbc’s first cousin), PDZ-RhoGEF, p190RhoGAP, and Vav1), while others were found specifically in immune cells (e.g., RhoA-GAP, Myo9B, and Rho-GEF7)." (PMID 34359851, 2021). "VAV1 has been shown to increase transcriptional activation of NFAT and NF-κB in rat basophilic leukemia cells; therefore, we wanted to investigate if the activation of these factors by nuclear VAV1 also contributes to its oncogenic function in PDAC cells." (PMID 41314543, 2025). "In a leukemia cell line and human peripheral blood, CXCL12-induced tyrosine phosphorylation of ZAP70 and Vav1 is essential for cell migration and adhesion." (PMID 23620790, 2013). "We next analyzed whether the expression levels of VAV1 and RASGRF2 genes were significantly altered in specific subgroups of patients affected of leukemia, lymphoma or myeloma." (PMID 20011522, 2009). "We could not rule out other mechanisms that Vav1 played in corresponding to the growth and development cancer, as Vav1 might also protect cells from apoptosis by enhancing anti-apoptotic Bcl2 transcription that we reported in leukemia cells." (PMID 24905577, 2014). "The take home message of these studies is that the human VAV1 and RASGRF2 genes do not show a consistent and generalizable change pattern in hematopoietic tumors such as lymphomas, leukemias or myelomas." (PMID 20011522, 2009).
lymphoma (13 papers, 2009 to 2024). A malignant (clonal) proliferation of B- lymphocytes or T- lymphocytes which involves the lymph nodes, bone marrow and/or extranodal sites. "An expression profiling study on DLBCL cell lines also demonstrated an association between increased VAV1 expression and a higher proliferative activity of lymphoma cells." (PMID 33562532, 2021). "Vav1 deficient patients and Vav1 loss of function lymphomas murine models of lymphomas show defects in F-actin accumulation, F-actin reorganization in response to TCR/CD28 co-engagement and the impairment in both positive and negative selection of T cells in the thymus." (PMID 33928032, 2021). "The Vav1 and Rasgrf2 gene deficiencies seem to contribute differently to these two lymphoma stages." (PMID 20011522, 2009). "Thus, the loss of the Vav1 proto–oncogene increases preferentially the frequency of “thymus–localized” lymphomas in one–year–old animals and, to a much lower extent, the percentage of “widespread” tumors." (PMID 20011522, 2009). "However, when combined with the inactivation of the Vav1 gene, the Rasgrf2 gene deficiency promotes a two–fold increase in the development of “widespread” lymphomas, shorter latency periods for the development of the disease, and enhanced mortality/sickness rates." (PMID 20011522, 2009). "As visualized by the IHC staining, Vav1 is found in the lymphomas as expected (likely representing the endogenous Vav1), but it is also expressed in epithelial cells, confirming the results obtained with the GFP staining." (PMID 35326399, 2022). "We are aware of one report of a murine PTCL‐GATA3‐like lymphoma in the literature, in which mature T‐cell lymphomas develop on a background of VAV1‐mutant transgenic (Tg)/p53nul mice." (PMID 35510955, 2022). "This conclusive result raises the possibility that the mere abnormal expression of the transgenic Vav1 in the epithelial tissue of an organ contributes to the generation of lymphomas." (PMID 35326399, 2022). "We then characterized the type of lymphoma that appeared in Rosa Vav1 mice." (PMID 35326399, 2022). "Thus, an induction of lymphomas is observed in Rosa Vav1 mice once Vav1′s expression is induced by Dox treatment." (PMID 35326399, 2022). "The mutation RhoA-G17V (a missense mutation leading to the change of the amino acid glycine on position 17 to valine) is common in CD4+ T-cells in lymphoma and is associated with autoimmunity, hyper-responsiveness of T-cells, and excessive TCR signaling via the Rho-GEF Vav1." (PMID 34359851, 2021). "Abnormal RHOAG17V-VAV1 signaling is seen in AITL and nPTCL-Tfh, but VAV1 mutations/fusions may play different roles in PTCLs other than Tfh lymphomas." (PMID 32704161, 2020). "Therefore, we wished to determine whether activation of Rac1 might play an indirect role in the contribution of Vav1 to development of Lymphomas." (PMID 35326399, 2022). "Therefore, we examined whether the expression of transgenic Vav1 protein affects ERK activation in the organs that develop lymphomas." (PMID 35326399, 2022). "Rac1-GTP levels did not change in tissues from Rosa Vav1 mice expressing the transgenic Vav1, while ERK phosphorylation increased in the lymphomas, suggesting that signaling pathways are evoked." (PMID 35326399, 2022). "Finally, complemental mouse models such as Fgd5-CreERT2, Vav1-Cre, CD19-Cre, or Mb1-Cre will be critical to determine which progenitor stage(s) are critical for lymphoma initiation by FBW7 deletion." (PMID 38485719, 2024). "In addition to frequent somatic mutations in RHOA and epigenetic modifiers, several studies have shown frequent alterations affecting TCR signaling-related genes, including CD28, FYN, PLCγ1 and VAV1 in cutaneous T-cell lymphomas, AITL and adult T cell leukemia/lymphoma." (PMID 30814910, 2019).
lymphoma (continued). "Selected Vav1 mutants and fusions lacking the c-terminal SH3 domain, when transgenically expressed in mouse T cells, lead to the development of PTCL resembling nodal TFH-derived lymphomas." (PMID 36845711, 2023).